KRT8P37 (keratin 8 pseudogene 37)
Gene: Transcribed processed pseudogene on chromosome 10 (8,513,687 to 8,515,106, reverse strand). Ensembl gene ENSG00000213771.
Diseases named in the same sentence as KRT8P37 in open-access papers:
KRT8P37 is named in the same sentence as 2 diseases in open-access papers, as found by Europe PMC text mining. Sharing a sentence is not in itself a finding about the gene and the disease.
KRT8P37 shares sentences with these, for which no sentence is quoted: asthma (1 paper); lymphoma (1).